GFAP (glial fibrillary acidic protein)
Diseases named in the same sentence as GFAP in open-access papers (continued):
Sharing a sentence is not in itself a finding about the gene and the disease.
infection (continued). "Studies in astrocytes have shown an increase at 60 days post-infection (dpi) in GFAP expression and protein levels in the brain, which suggests that hRSV infection promotes astrocyte activation." (PMID 39203555, 2024). "The results demonstrated the presence of astrogliosis in lpr and gld mice at 9 days post-infection, while the numbers of GFAP+ were insignificantly increased in the wild-type mice." (PMID 39339840, 2024). "Following an injury or infection, astrocytes undergo activation (astrogliosis), which is demonstrated by a rise in the cytoskeletal protein named glial fibrillary acidic protein (GFAP)." (PMID 39286668, 2024). "After infection with T. gondii, the astrocyte-specific marker glial fibrillary acidic protein (GFAP) level, is upregulated, showing widespread astrocyte activation." (PMID 39723133, 2024). "As the mice that received the dual treatment still displayed higher numbers of GFAP+ cells 12 weeks post-infection, it can be inferred that this increase is sustained over time." (PMID 38542396, 2024). "Toward this direction, the combined expression of the astrocytic markers GFAP and S100β was assessed through immunofluorescence experiments at 14 days post infection." (PMID 39468302, 2024). "Immunofluorescence staining revealed a different pattern of GFAP+ enteric glial reactivity in the myenteric plexuses of the colon tissue at 9 days post infection." (PMID 38849869, 2024). "Whereas infection with both viral strains induced astrogliosis in all CNS regions at both time points, HIV-1CH040 infected mice at 2-weeks post-infection showed the highest GFAP+ fluorescence signal consistently across CNS regions." (PMID 38945996, 2024). "This theory was proven in vitro, when after the infection of human astrocytes by GFAP of:NeuroD1-IRES-GFP retrovirus, NeuroD1-positive cells also express positivity for NeuN, a marker of functional neurons." (PMID 38481632, 2024). "During infection, EGCs acquire a distinct molecular state similar to astrogliosis involving cell cycle entry and GFAP upregulation, enabling them to exert local immunomodulatory effects on surrounding cells." (PMID 38957473, 2024). "Conversely, GFAP expression in samples from BZ-treated animals exhibited control-like glial morphology with a dense network, which was also preserved in relapsed infections." (PMID 38782898, 2024). "In contrast, ccr2 transcripts in the brain were similar in control CCL2fl/fl mice and GFAP-Cre CCL2fl/fl mice during infection." (PMID 38206985, 2024). "To this end, we immunostained sections of brain and spinal cord of ODC-OVA; VE-cadherin-GFP knock-in mice for glial fibrillary acidic protein (GFAP) on day 7 after LCMV-OVA infection." (PMID 37730744, 2023). "We infected U373 with VSV-G/GAGi or GAGi.Nef- and confirmed a comparable infection efficiency and Nef-induced GFAP down-modulation in VSVG/GAGi-infected cells as before." (PMID 36818564, 2023). "Glial fibrillary acidic protein showed a statistically significant increase in the brain white matter of dogs in the infection and contact groups at the early and late periods, suggesting potential proinflammatory conditions in the brain." (PMID 37877548, 2023). "Increased GFAP expression serves as an important characteristic of reactive astrocytes that are activated in pathological processes such as hypoxia, infection, and trauma." (PMID 38075277, 2023). "One possible mechanism is that the infection damaged the astrocytes, exposing and releasing many GFAP antigenic determinants, leading to antibody production and secondary autoimmune responses." (PMID 37205100, 2023). "The expression of JCPyV VP1 capsid protein was confirmed at day 7 post-infection and shown to co-localize with astrocytic marker, glial fibrillary acidic protein (GFAP) by IFA." (PMID 37815349, 2023). "GFAP labeling showed that an in utero infection compromises glial cells responsible for midline axon guidance." (PMID 38140578, 2023).
infection (continued). "After disruption of the blood–brain barrier by infection, these cells can infiltrate the CNS and cause GFAP-specific CD8 + T cell-related inflammation and GFAP-IgG production." (PMID 37016352, 2023). "With a comparable infection effeciency, VSVG/NLGi.Nef- infection showed a high level of GFAP protein expression than VSVG/NLGi infection in human primary fetal astrocytes (HPA)." (PMID 36818564, 2023). "70–80% of PFC GFAP+ astrocytes at the site of infection were colabelled with GFP in GFAPcre− mice infused with AAV5-GFP-DIOCMV-DTRflag." (PMID 37461693, 2023). "Compared to VSVG/GAGi infection, VSV-G/GAGi.Nef- infection showed a higher level of GFAP protein expression (~1.4 fold)." (PMID 36818564, 2023). "An ex vivo study exposing primary human cortical tissue slices to SARS-CoV-2 showed that 90% of infected cells expressed GFAP and aquaporin 4, suggesting a dominant infection of astrocytes in comparison to neurons and other glial cells." (PMID 37516868, 2023). "We demonstrated astrocyte activation and infection according to the higher expression of GFAP and colocalization with viral nucleic acid signals in severe mice." (PMID 36735880, 2023). "The results of our in vivo experiments show that GFAP expression was downregulated whereas SLC7A11 was upregulated after TgCtwh3 infection." (PMID 37651502, 2023). "We observed a total of 2.2 ̇ 1013 fluorescent counts in the naïve specimen compared to 3.0 ̇ 1013 fluorescent counts in the infected specimen when assessing the cingulate cortex area indicating an increase of 38% in GFAP reactivity upon infection." (PMID 35774409, 2022). "During intestinal inflammation and infection, EGCs become “reactive” (reactive gliosis) and undergo changes in morphology, GFAP expression, and cytokine release, which contribute to neuroinflammation and barrier dysfunction." (PMID 36501151, 2022). "Expression of p24 (red) was visualized using immunocytochemistry in astrocytes stained with astrocyte marker, GFAP (green) following 7 days infection with pseudotyped HIV-1 (1000 RT)." (PMID 35784841, 2022). "The results showed that the transcription level of GFAP increased in the DE205B infection group (p < 0.05), compared to levels observed in the RS218 (p < 0.01) infection group." (PMID 36143390, 2022). "This pattern of retinal neuronal expression was also evident at 8 days following infection for GFAP-Insm1-mCherry, GFAP-Atoh7-Ascl1-mCherry, and GFAP-Atoh7-Brn3b-mCherry." (PMID 36200040, 2022). "We report the case of a patient with a positive and high level of GFAP antibodies in the cerebrospinal fluid (CSF), following a Brucella infection." (PMID 35990675, 2022). "The number of GFAP-positive hepatic stellate cells significantly increased during the course of the infection." (PMID 36355906, 2022). "SARS-CoV-2 (MA10) infection showed a trend towards increased GFAP expression in the hippocampus of 12-week old male BALB/c mice after 3 days of infection compared to mock-treated mice." (PMID 36680154, 2022). "Additional evidence of increased neuroinflammation in infection was seen through glial fibrillary acidic protein (GFAP) IHC, which was upregulated in infected animals, as compared to age-matched controls." (PMID 35365631, 2022). "In contrast, in our study the amount of GFAP protein levels by immunohistochemistry obviously increased with age but remained largely unaffected by infection with SARS-CoV-2." (PMID 35785352, 2022). "At 14 h after infection, the densities of GFAP- and Iba-1-expressing cells were increased in both genotypes compared with the findings in the mock-infected controls." (PMID 33318141, 2021). "To further confirm the existence of intermediate stages during the reprogramming process, we enriched GFP+ cells in wild-type retinas 5.5 days post-infection with GFAP-Math5-Brn3b-GFP AAVs, and subjected them to scRNA-seq analysis." (PMID 34671605, 2021).
infection (continued). "Based on the determined onset time of MG reprogramming, we next searched for the initial and intermediate states of MG transdifferentiation in the Brn3b-GFP reporter mouse line at 4–6 days following infection with GFAP-Math5-Brn3b-tdTomato AAVs." (PMID 34671605, 2021). "Two weeks after infection with the GFAP-GFP AAVs, numerous MG located in the inner nuclear layer (INL) of the retina were seen to express GFP and display a typical Müller cell morphology with processes spanning both the inner and outer retinal layers." (PMID 34671605, 2021). "In response to infection and in certain inflammatory scenarios, Müller cells and retinal astrocytes undergo reactive gliosis, being GFAP expression in those cells a typical feature of retinal stress." (PMID 33562020, 2021). "Infection with S. mansoni increased the number of GFAP- and Iba-1-positive cells, whereas soma eccentricity and cell extent were altered only in GFAP-positive cells." (PMID 34303703, 2021). "Infection of the ONC eyes with GFAP-Math5-Brn3b-GFP AAVs (treated) triggered obviously stronger VEP responses than the control treatment." (PMID 34671605, 2021). "Control-transduced astroglia remained committed to their lineage as revealed by astrocyte morphology and GFAP expression at 2 months post-infection (mpi; >90% of DSRED+ cells)." (PMID 34592167, 2021). "Astrocytic GFAP increases in expression initially during the early chronic stage of infection, remains steady between 14 and 28dpi, and then experiences a significant increase in expression by 56dpi (top)." (PMID 33816350, 2021). "In this study, AAV vector was used to express Neurog2 under the direct control of a human GFAP promoter for the specific astrocytes infection." (PMID 33649354, 2021). "GFAP+ cells were detected from 3 dpi on, with mild changes in their distribution and relative abundance during the infection course and between infected groups." (PMID 34199167, 2021). "The quantitative analysis found that at 3 days post-NeuroD1-mCherry viral injection (3 dpi), 92.1 ± 3.1% of NeuroD1-mCherry infected cells were GFAP-positive, indicating preferential infection of astroglial population guided by GFAP::Cre viruses." (PMID 33250718, 2020). "The infection with Streptococcus pneumoniae resulted in an increased GFAP+ cell density in Fpr1−/− and Fpr2−/− mice." (PMID 33121515, 2020). "Age, trauma, infection, and autoimmune response increase the number of astrocytes and induce rapid synthesis of GFAP." (PMID 33029280, 2020). "Our results show that 10 weeks after infection, in the infected group, there was significant increase in Iba-1 and GFAP expression in spinal cord tissue." (PMID 32230725, 2020). "Infected animals exhibited significantly more GFAP + astrocytes in the SNpc, SNr, and ST with apparent hypertrophic/reactive morphology at 8 weeks post infection." (PMID 31531390, 2019). "In the prior study in the pigtail macaque, vertical transfer of the Cambodian strain of ZIKV also resulted in an increase in GFAP- stained astrocytes in the white matter of the cortex as observed at six weeks after infection (at near-term gestation)." (PMID 30657788, 2019). "The rate of infection, as evaluated by colocalization with astrocytic (GFAP) or neuronal (NeuN) markers was 48.6 ± 6.6% (N = 7) for astrocytic Cre, and 89 ± 5.2% (N = 5) for neuronal Cre." (PMID 31273206, 2019). "A positive correlation was detected between the percentage of infected astrocytes (GFP/GFAP positive cells) and the freezing response 30 days after infection." (PMID 31273206, 2019). "In this sense, the temporal profile of spinal cord GFAP mRNA expression over the course of disease (5–40 days post-infection) was investigated." (PMID 31138231, 2019). "To evaluate the relative infection of astrocytes versus microglia, we also measured the proportions of viral Ag-positive area relative to GFAP- or IBA1-positive areas." (PMID 29491163, 2018).
infection (continued). "GFAP levels, on the other hand, were lower in sulfadiazine-treated compared to untreated animals, compatible with a reduction of the infection-related neuroinflammatory response." (PMID 30068357, 2018). "Reactive gliosis was also characterized in our experimental approach of infection by the presence of clusters of astrocytes (GFAP+ cells)." (PMID 29950590, 2018). "Despite the longer post-infection time, most infected cells appeared morphologically normal, though a small number of astrocytes were misshapen and the GFAP staining pattern suggested the cytoskeletal filaments were condensed." (PMID 28645311, 2017). "Previously, we reported that depletion of macrophages enhanced infection of GFAP+ astrocytes in the spinal cords of HSV-1 infected mice as compared to mock-depleted mice." (PMID 28542613, 2017). "The present study found that TGF-β1, TG2, S100B and GFAP were significantly elevated during early infection at 8 wpi, which was similar to results of our previous study." (PMID 29273062, 2017). "Closer examination of two gH-positive areas displayed a downregulation of GFAP immunolabel within the aggregates, while neighboring astrocytes showed signs of early infection and upregulation of GFAP." (PMID 26491149, 2016). "The upregulation of GFAP can be observed in reactive astrocytes; such upregulation can be induced by traumatic injury, edema, inflammation, or infection in the brain." (PMID 27517922, 2016). "Astrocytes are crucial in regulating responses to infection and neural injury, and respond to such challenges by becoming “reactive” and up-regulating expression of GFAP, in a process termed astrogliosis." (PMID 27022620, 2016). "In vivo, rAAV6 transduced >90% of GFAP+ astrocytes in the infected brain areas, with minimal infection of neuronal cells." (PMID 27891076, 2016). "At 3 days after infection, GFAP expression in white matter increased, with staining located within astrocyte dendrites." (PMID 27258396, 2016). "In brains that have experienced traumatic injury, inflammation, or infection, the expression of TN-C is enhanced simultaneously with the expression of GFAP in reactive astrocytes." (PMID 27517922, 2016). "Increased expression of GFAP is indicative of reactive astrogliosis – as defined by glial cell activation due to injury or pathological processes including hypoxia, infection and trauma." (PMID 27616338, 2016). "Western blotting also showed that GFAP expression was significantly higher in the infected group than the controls from day 7 (P < 0.05) to day 42 (P < 0.01) after infection." (PMID 25961032, 2015). "In this study, we observed a significant increase in the level of GFAP in the brains of BALB/c mice from day 7 to day 42 day after infection, suggesting that the astrocytes were activated after A. cantonensis infection." (PMID 25961032, 2015). "In previous works, we showed that in acutely-infected C3H/He mice, astrocytes (GFAP+ cells) and macrophages/microglial cells (F4/80+) are targets of infection." (PMID 25695249, 2015). "Compared with acute infection, a reduced number of T. cruzi-bearing GFAP+ cells was observed in the CNS during the chronic phase of infection." (PMID 25695249, 2015). "Prior to the onset of clinical symptoms, at 108 days post-infection, we evaluated GFAP expression in the brains of treated and mock-treated mice to determine levels of astrocytosis." (PMID 26134409, 2015). "GFAP expression in the astrocytes was significantly higher in the hippocampus as determined by staining with rabbit anti-GFAP on day 14 after infection." (PMID 25961032, 2015). "Immunofluorescence staining of brain sections from mice prepared 28 days following infection with A. cantonensis showed that the expression of GFAP and Shh was significantly increased in the cytoplasm of astrocytes." (PMID 25961032, 2015). "Similar to the mRNA expression, immunohistochemical analysis revealed increased GFAP expression in the WT mice at day 8 after infection." (PMID 24750819, 2014).
infection (continued). "The mRNA expression of GFAP was increased in WT mice at day 8 after infection compared to corresponding mock-infected mice." (PMID 24750819, 2014). "Astrocytes highly express GFAP in their end-feet and extend it to injured regions, where cerebral blood vessels or neuronal cells are injured in pathological conditions such as infection and transient ischemia." (PMID 24722459, 2014). "Activation of glial cells, as demonstrated by increased GFAP staining, is a common feature of many types of neural insults including trauma, toxins, neurodegenerative triggers, or infection." (PMID 23585733, 2013). "In contrast to the lungs, little to no leukocyte recruitment to the brain was observed over time, though Iba-1 and GFAP staining showed that microglia and astrocytes were activated as soon as 1 hour post-infection." (PMID 23874613, 2013). "In response to infection or injuries, the activation of astrocytes can be characterized by their upregulation of intermediate filaments, such as GFAP, vimentin." (PMID 23144903, 2012). "Infection with SIVmac17E-Fr resulted in an increase in the intensity of GFAP staining, whereas CNPase1 and FF1 expression levels were greatly reduced across all tissue regions." (PMID 22403025, 2012). "In Ntv-a mice, the nestin promoter directs infection to neural/glial progenitor cells, while in Gtv-a mice, the glial fibrillary acidic protein (GFAP) promoter directs infection mainly to astrocytes." (PMID 21949886, 2011). "Using Western blot, we detected that compared to naive rats (0.22±0.04) and mock infected rats (0.2±0.03), GFAP expression was significantly increased in VZV infected rats at post-infection day 3 (0.68±0.15)." (PMID 21969850, 2011). "Immunohistochemistry indicated that compared to naive rats and mock infected rats, GFAP staining was significantly increased in the spinal cord of VZV infected rats at post-infection 1 week (P1), peaked at P2, and thereafter maintained at high level till P8." (PMID 21969850, 2011). "Both HCV core and NS3 proteins were detectable in cytoplasm of GFAP (astrocytes) and Iba-1 (microglia) immunopositive cells compared to mock infection." (PMID 20877724, 2010). "Similarly, reductions in GFAP were more pronounced among participants with N-PASC ≤1.5 years after infection (69.0% decrease, P < 0.001 versus 16.3% decrease, P = 0.33 among those within >1.5 years of infections)." (PMID 41494242, 2026). "However, in response to trauma, infection, or neurodegenerative diseases, astrocytes can become reactive, leading to the upregulation of glial fibrillary acidic protein, a marker of reactive astrocytes." (PMID 41223008, 2025). "To determine whether EcoHIV disrupts white matter astrocytes in a Nef-mediated mechanism, we examined expression of GFAP within the corpus callosum at the injection site 5-wk post infection via confocal microscopy." (PMID 39532531, 2025). "Therefore, we utilized colocalization to determine the site of viral invasion at 72 h post infection using GFAP/MMP-9, neuronal nuclei (NeuN)/MMP-9, and CD31/MMP-9." (PMID 40176142, 2025). "In order to evaluate whether WNVNY99 infection of astrocytes affects their morphology and survival, hNGC infected for 7 days were immunostained with an antibody directed against GFAP." (PMID 41419758, 2025). "Apparently, NfL levels tend to increase along time in severe/critical cases once it is related to neuronal injury and disease progression, while GFAP may indicate the astrocytic activation and injury as a first CNS response to infection." (PMID 37996731, 2024). "Infection of GFAP and MAP2-positive cells was confirmed by the use of orthogonal sections." (PMID 38514653, 2024). "A similar mechanism was also observed in the case of human adenovirus-41 (HAdV-41) infection, where EGCs had high expression of GFAP under the influence of serotonin released from enterochromaffin cells that expressed HAdV-41-specific coxsackievirus and adenovirus receptor (CAR)." (PMID 38957473, 2024).